AFP (alpha fetoprotein)
Diseases named in the same sentence as AFP in open-access papers (continued):
Sharing a sentence is not in itself a finding about the gene and the disease.
tumor (continued). "The aim of this study was to assess the potential of using the AFP change after the first TACE in the prediction of complete tumor necrosis." (PMID 37568778, 2023). "In mixed GCT, the proportion of YST components in a tumor specimen demonstrated positive correlation with serum AFP levels (r = 0.575)." (PMID 37958463, 2023). "Factors such as waitlist time, tumor burden, and alpha-fetoprotein response to downstaging therapy have been shown to influence post-transplant outcomes." (PMID 37444618, 2023). "Specific to the AFP score 2 group, all the patients had an AFP level < 100 ng/mL and the largest tumor size ≤ 3 cm, facilitating easy clinical application." (PMID 36967432, 2023). "Several new blood-based biomarkers, including des-gamma-carboxy prothrombin, lens culinaris agglutinin-reactive AFP, plasma microRNA expression, methylated DNA markers, circulating tumor DNA, and circulating tumor cells, have been studied." (PMID 37899451, 2023). "Other than its role in regulating tumor cell function, the AFP-high HCC samples exhibited altered immunity-related pathways." (PMID 37336873, 2023). "Before PSM (185 OAR and 142 MIAR cases), compared to OAR, MIAR was significantly associated with higher BMI, lower ASA class, lower ICGR15, lower Child–Pugh class, smaller tumor size, lower AFP and DCP levels, and more favorable tumor stage." (PMID 37190148, 2023). "The tumor showed a positive immunophenotype for AFP and histology presenting features of hepatocellular differentiation, known as an AFP-producing tumor." (PMID 37950062, 2023). "Tumor-derived AFP(tAFP) stimulated M0 macrophage polarization into M2 macrophages and inhibited M1 macrophages to phagocytize HCC cells." (PMID 36911723, 2023). "In our TAA-induced HCC model, elevated biochemical tumor markers, AFP and CA19.9 are other evident signs of HCC development." (PMID 36809998, 2023). "High expression of VASP cloud be combined with some classic tumor markers (such as prostate-specific antigen, carcinoembryonic antigen, alpha-fetoprotein, etc.) to evaluate the prognosis of patients." (PMID 37962042, 2023). "AFP, tumor diameter, and tumor number are well-known indicators affecting outcomes after LR for HCC and were included in several clinical guidelines." (PMID 37152055, 2023). "The creation of AFP-epitope optimization will enhance the activation of AFP-specific CD8 T cells which will lead to the cross-recognition of native AFP epitopes on HCC tumor cells generating an antitumor effect." (PMID 37759769, 2023). "The serum tumor markers are serum alpha fetoprotein (S-AFP), serum human chorionic gonadotropin (S-hCG), and S-LDH." (PMID 36835562, 2023). "Second, as far as the tumor's biological characteristics are concerned, AFP level, MVI, and satellite nodules were higher in the Group B than in the Group A (p < 0.05), reflecting that the tumor biological characteristics of Group B were more aggressive." (PMID 36540041, 2023). "Further, on univariate analysis, factors contributing to PFS included a decrease in AFP values from Atezo + Beva initiation and relative tumor volume at the second radiological response evaluation." (PMID 37190231, 2023). "Identified clinical features related to RFS included age, tumor number, tumor size, tumor differentiation and smoking/alcohol assumption history, and AFP and DCP were both significantly related to RFS." (PMID 37496285, 2023). "Pathological differentiation, tumor size, AFP, TNM stage, NLR score, and ALBI grade were identified as significant indicators of OS in the univariate analysis." (PMID 37208618, 2023).
tumor (continued). "The OSASH score was constructed with 4 variables profiling the tumor burden (tumor multiplicity) and biology (incomplete tumor “capsule,” mosaic architecture, and AFP)." (PMID 37191923, 2023). "In contrast, the PAT group patients had higher tumor malignancy (AFP ≥ 400 ng/mL, satellite nodules, and vascular invasion) than those in the non-PAT group." (PMID 37359534, 2023). "The univariate and multivariate analysis showed that AST/ALT ratio, AFP, and tumor numbers were independent prognostic indicators for OS." (PMID 36944920, 2023). "Consistent with the c-MYC/Mcl1 prevention model, the AFP immunization also prevented cMet/β-catenin-induced HCC tumor formation (A C, and D, P < 0.05)." (PMID 37040183, 2023). "Univariate analysis identified tumor burden>8 cm, pre-LT AFP >400 ng/ml, pre-LT PIVKA-II >240 mAU/ml, tumor histopathologic grade III, and present pre-LT TACE as the significant risk factors for DFS." (PMID 37988413, 2023). "There are reports of conjugates utilizing other forms of AFP which have demonstrated anti-tumor effects both in vitro and in vivo." (PMID 37016369, 2023). "Before PSM (163:113), compared to OAR, MIAR was significantly associated with higher BMI, a lower ASA class, lower ICGR 15, smaller tumor number and size, more favorable tumor stages, and higher AFP and DCP levels." (PMID 37190148, 2023). "Further transcriptomic and proteomic analyses showed that miR-135b-5p is closely associated with tumor stemness properties, similar to the molecular characteristics of patients with HCC with high AFP levels." (PMID 36755690, 2023). "AFP is a key tumor marker of HCC, and it is also included as a factor in many prognosis models for HCC patients." (PMID 37689775, 2023). "If we focus on preoperative findings, such as tumor size, tumor number and AFP value adding the information given by TLR of 18F-FDG PET/CT allows to estimate the risk of tumor recurrence more accurate than the established classifications Milan and UTS." (PMID 35451699, 2023). "When we set the limits of tumor diameter as 4 cm and AFP level to 1000 ng/mL, the estimated 5-year survival is calculated at 60% according to the Metroticket calculator." (PMID 37909200, 2023). "Other parameters such as etiology, degree of tumor differentiation, microvascular invasion, AFP, BCLC stage, tumor size, multiple nodules, and satellites did not correlate significantly with high hsa-miR-3180 expression." (PMID 37051592, 2023). "As a well-established tumor biomarker, AFP has a high specificity in the early detection of HCC and is widely used for the diagnosis and surveillance of HCC." (PMID 36766518, 2023). "For the sake of a more accurate model and to achieve a better classification, targeted therapy, AFP expression levels and tumor stage were eventually included in the nomogram here." (PMID 38023207, 2023). "After surgery, AFP levels are expected to decrease below the upper reference range, and failure to do so indicates unsuccessful tumor resection or early recurrence." (PMID 37686577, 2023). "AFP level > 1000 ng/mL, largest tumor size ≥ 8 cm, vascular invasion, and MELD score ≥ 15 were associated with overall survival." (PMID 36967432, 2023). "Alternatively, patients with ascites often had larger tumor burdens, higher rates of vascular invasion or metastasis, and higher AFP levels." (PMID 36765711, 2023). "In the current study, we compared the differences between the MVI-positive group and MVI-negative group, and we found that age, multiple tumors, AFP level, NEU level and tumor diameter were independent risk factors for predicting MVI status." (PMID 37118720, 2023). "Tumor recurrence (at 30 months) as well as alpha-fetoprotein (at 36 months) was significantly reduced as a result of BCAA use; however, overall mortality was unaffected." (PMID 36310325, 2023).
tumor (continued). "Several serum tumor markers, such as carcinoembryonic antigen (CEA), cancer antigen 19-9 (CA19-9), and alpha-fetoprotein (AFP), are also used to predict the risk of gastrointestinal cancer, whereas their sensitivity and specificity are still unsatisfactory." (PMID 36765913, 2023). "When a patient had a single tumor, a tumor diameter less than 7 cm and a serum AFP level less than 400 IU/L, he was more likely to be MVI negative (H, H, H and H)." (PMID 37118720, 2023). "Independent risk factors for both TTP and OS included portal vessel invasion, extrahepatic metastasis, tumor number, AFP level, longest tumor diameter, and PNI." (PMID 36675418, 2023). "Our data showed that the combination of M-CTC and Ki67 correlated with AFP, tumor size, tumor number, Edmondson grade, tumor capsule, MVI, PVTT, BCLC stage and VCE." (PMID 36600214, 2023). "Tumor markers, including cancer antigen 125, alpha fetoprotein, and β-human chorionic gonadotropin, were normal." (PMID 36998093, 2023). "In-vitro detection is mainly detecting some tumor markers (such as alpha-fetoprotein, carbohydrate antigen, microRNA, carcinoembryonic antigen, and exosomes, etc.)or using some immune complex tags." (PMID 37149605, 2023). "High levels of AFP indicate poor differentiation and high invasiveness of initial HCC, which are also associated with tumor progression after treatment." (PMID 36910605, 2023). "Although tumor markers such as AFP have been developed for the diagnosis of HCC, which has effectively improved the early diagnosis rate, there are still some patients who are missed." (PMID 36793272, 2023). "After 6 cycles of therapies, the tumor responded well and shrank significantly, and level of AFP decreased from 410,302 ng/ml to 13.9 ng/ml." (PMID 37007075, 2023). "Ki67 is regarded as a proliferation index of the primary HCC in evaluations of tumor malignancies and is related to tumor size, high AFP level, and TNM stage." (PMID 37337648, 2023). "Models preMORAL (NLR, AFP, maximum tumor diameter) and postMORAL (tumor grade, MVI, maximum tumor diameter and count) predict the risk of recurrence after transplantation and divide HCC recurrence risk into low, medium, high, and very high." (PMID 37369911, 2023). "In conclusion, AFP levels, tumor location, and CT attenuation values of tumors in the portal venous phase were independent predictors for discriminating GHA from GA." (PMID 37538113, 2023). "The univariate analyses found that the mALBI grade, intrahepatic tumor number, macrovascular invasion, AFP value, the number of systemic therapy lines, and therapeutic efficacy of first-line therapy were associated with OS." (PMID 37958471, 2023). "Compared with late recurrence, early recurrence mainly originates from intrahepatic metastasis and is driven by aggressive characteristics of the primary tumor such as tumor size, multiple tumor lesions, vascular invasion or higher serum AFP level." (PMID 36826093, 2023). "In other words, Macrovascular invasion, preoperative serum alpha-fetoprotein (AFP) level, tumor size, histopathologic grading were significant factors for survival and tumor-free survival by univariate analysis." (PMID 36564609, 2023). "Traditionally, decision-making is based on pre-chemotherapy levels of serum tumour markers, alpha-fetoprotein (AFP), human chorionic gonadotrophin (hCG), lactate dehydrogenase (LDH) and imaging." (PMID 36768818, 2023). "Third, our study only included AFP‐negative HCC patients of BCLC 0, BCLC A and BCLC B. For HCC patients with advanced tumor (BCLC C) or AFP‐positive, our results also need to be further demonstrated by further studies." (PMID 38130028, 2023).
tumor (continued). "High Ki67 expression correlated with AFP ≥ 400 ng/mL (P = 0.015), tumor size ≥ 5 cm (P = 0.012), incomplete tumor capsule (P < 0.001), MVI (P = 0.001), PVTT (P = 0.003), advanced BCLC stage (P = 0.01), and vessel carcinoma embolus (VCE) (P = 0.001)." (PMID 36600214, 2023). "The combination of tumor location, AFP, and PCA yielded 86.4% sensitivity and 81.9% specificity with an AUC of 0.903." (PMID 37538113, 2023). "Incorporating AST, ALT, and AFP levels, in addition to the tumor burden, into our model helps to reflect both tumor status (burden and biology) and hepatic function status." (PMID 37200967, 2023). "The results of stratified analysis also demonstrated that, to some extent, the subjects with tumours < 5 cm or lower AFP revealed better clinical outcomes after TACE, consistent with previous reports." (PMID 36631744, 2023). "Univariate analysis revealed that Child-B, tumor number ≥ 2, tumor diameter ≥ 10 cm, AFP ≥ 400 ng/ml, ALP ≥ 125 U/L, platelet ≥ 100000/μL, ALT ≥ 40 U/L, worse BCLC stage, PVTT, and TACE were significant risk factors for death in this patient population." (PMID 37818373, 2023). "Another retrospective analysis suggested that high levels of AFP (≥20 ng/dL) and DCP (≥40 mAU/mL) were independent risk factors for tumor relapse and DFS in patients with HBV-related HCC after curative resection." (PMID 37519791, 2023). "The elevated expression of RRM2 in HCC was significantly correlated with T stage (P <0.05), pathologic stage (P <0.05), tumor status (P <0.05), histologic grade (P<0.001), and AFP (P <0.001)." (PMID 37056349, 2023). "The aim of this study was to evaluate the predictive value of AFP response to LRT and use it to stratify the tumor recurrence risk of HCC patients after LDLT." (PMID 36900345, 2023). "Numerous liver tumor lesions developed in tumor control, AFP immunization, and anti–PD-L1 monotherapy mice." (PMID 37040183, 2023). "Serum levels of PIVKA-II and AFP decreased significantly after LT and increased in patients with tumour recurrence." (PMID 37024609, 2023). "In the survival analysis of all patients, we found that AFP, tumor size, N and M stage, and therapy strategy were independently associated with patient OS." (PMID 37409255, 2023). "We found that the independent prognostic factors were age, NEU, multiple tumors, AFP level and tumor diameter." (PMID 37118720, 2023). "LI-RADS, serum AFP level, and maximum tumor diameter were finally selected as the basic factors for the nomograms and the CEUSS model by excluding collinearity and selecting simple markers." (PMID 37519810, 2023). "Diagnostic work-up involves ultrasound examination as well as serum tumor markers alpha fetoprotein, beta-human chorionic gonadotropin and lactate dehydrogenase, and particularly the novel marker M371." (PMID 37051441, 2023). "Further boxplot results showed that HCC patients who died and had a TNM stage III-IV, AFP > 300 ng/ml, and tumor size > 5 cm tended to have higher TRscores (p < 0.05)." (PMID 37208604, 2023). "There has also been a growing movement to incorporate markers beyond tumor size alone into the decision of patient eligibility for LT, particularly the use of AFP levels." (PMID 38001637, 2023). "The rate of change in AFP levels upon treatment was 84.98%(17.59-96.74%) which reflected tumor response to 4 cycles of NAC before surgery." (PMID 37124543, 2023). "Other tumor markers, such as the des-gamma-carboxyprothrombin (DCP) and the Lens culinaris agglutinin-reactive fraction of AFP (AFP-L3), have been used to increase the diagnostic accuracy of AFP." (PMID 37894965, 2023). "Univariate and multivariate Cox analysis results of all patients before PSM showed AFP, tumor size, N stage, M stage, and treatment were considered as independent predictors of OS." (PMID 37409255, 2023). "The patient had an age of 8 months, a preoperative AFP of 64.6 ng/ml, and normal testicular tissue after complete surgical resection of the tumor." (PMID 36795187, 2023).
tumor (continued). "The aim of this study was to evaluate the clinical contribution of protein induced by vitamin K absence or antagonist-II (PIVKA-II) for HCC monitoring after liver transplantation (LT) and compare it with AFP, a routinely used tumour marker." (PMID 37024609, 2023). "AFP is one of the first discovered tumor biomarkers and is widely applied by clinical guidelines for diagnosis of HCC and recurrence surveillance after surgery." (PMID 36814805, 2023). "This analysis underscored the pivotal role of age, gender, AFP levels, tumor grade, tumor stage, tumor size, surgical interventions, and the judicious use of chemotherapy as determinants of OS." (PMID 38001570, 2023). "Multivariate analysis identified that tumor numbers > 3, AFP ≥ 400 ng/ml, PLT < 100 × 10^9 ng/ml, and ALP > 150U/L were independent risk factors of OS, while prior surgery was an independent protective factor." (PMID 37287040, 2023). "AFP is the most commonly used tumor marker in clinical and has a degree of specificity for the diagnosis of HCC." (PMID 37182122, 2023). "A recent research has proved that BCLB stage, serum of AFP, tumor location, and other factors are significant factors for tumor response after TACE in HCC patients, which is similar to our findings." (PMID 36923427, 2023). "SKA1 expression levels were significantly correlated with weight, age, T stage, N stage, M stage, tumor status, AFP levels, pathologic stages, histologic grade, OS, DSS, and PFI of the HCC patients." (PMID 37746945, 2023). "Studies have shown that liver metastases frequently occur as a pathophysiology of AFP-GC, and even if the tumor is diagnosed in the early phase, the prognosis is poor." (PMID 37354221, 2023). "In this study, we observed a negative correlation between TMEM88 expression and unfavorable prognostic characteristics of HCC, including advanced tumor stage, poorer differentiation grade, and higher serum AFP level." (PMID 37091140, 2023). "More recently, scores incorporating alpha fetoprotein (AFP) levels as a surrogate of tumor biology have been proposed to better assess patients eligibility for LT." (PMID 37240873, 2023). "Factors such as age, the size and border of the tumour, calcification, intratumoural haemorrhage and vessels, vascular invasion, the presence of distant metastasis and elevation of AFP differ significantly between these two types of pancreatic neoplasms." (PMID 37190144, 2023). "Tumor markers, including AFP and Beta-HCG, were important tools used in the diagnosis, relapse, and follow-up." (PMID 37182921, 2023). "Univariate and multivariate analyses confirmed that preoperative serum SP70 level, serum AFP, tumor diameter and microvascular invasion were independent prognostic factors of RFS." (PMID 37091138, 2023). "The SII–ALBI 2 class had a remarkably higher alpha-fetoprotein (AFP) level, a bigger largest size of the tumor, and a higher BCLC C stage versus the other groups (P < .05)." (PMID 36620927, 2023). "We studied the correlation between MRPL48 expression and the clinical and pathological features of HCC patients, including the T classification, the pathological tumor grade, the AFP level, and the vascular invasion of tumors." (PMID 38093387, 2023). "The level of AFP also to a certain extent reflects tumor size, and its dynamic change has a particular relationship with cancer." (PMID 38087278, 2023). "Results of the linear regression analysis showed a positive correlation between ctDNA VAF and the size of the largest tumor as well as AFP level." (PMID 37298294, 2023). "Elevated Adam8 levels are associated with increased serum Alpha-fetoprotein (AFP), advanced tumor stage, poor differentiation, increased tumor recurrence and metastasis, and reduced survival." (PMID 37370863, 2023). "Based on the expression levels of four proteins: CETP, HGFL, L1CAM, and LAIR2, combined with tumor diameter, serum AFP, and GGT concentrations to establish a preoperative MVI status prediction model for HCC patients." (PMID 38049860, 2023).